NR4A1 (nuclear receptor subfamily 4 group A member 1)
Description:
Orphan nuclear receptor. Binds the NGFI-B response element (NBRE) 5'-AAAGGTCA-3'. Binds 9-cis-retinoic acid outside of its ligand-binding (NR LBD) domain. Participates in energy homeostasis by sequestrating the kinase STK11 in the nucleus, thereby attenuating cytoplasmic AMPK activation. Regulates the inflammatory response in macrophages by regulating metabolic adaptations during inflammation, including repressing the transcription of genes involved in the citric acid cycle (TCA) (By similarity). Inhibits NF-kappa-B signaling by binding to low-affinity NF-kappa-B binding sites, such as at the IL2 promoter. May act concomitantly with NR4A2 in regulating the expression of delayed-early genes during liver regeneration (By similarity). Plays a role in the vascular response to injury (By similarity). In the cytosol, upon its detection of both bacterial lipopolysaccharide (LPS) and NBRE-containing mitochondrial DNA released by GSDMD pores during pyroptosis, it promotes non-canonical NLRP3 inflammasome activation by stimulating association of NLRP3 and NEK7.
Synonyms: Nur77; GFRP1; HMR; TR3; N10; NAK-1; NGFIB; NP10
Tractability: Small molecule: a structure with a bound ligand is known; a high-quality ligand is known; it belongs to a druggable protein family. PROTAC: ubiquitination databases record sites on it; a small molecule that binds it is known.
Target class: Nuclear receptor; Transcription factor; Nuclear hormone receptor subfamily 4; Nuclear hormone receptor subfamily 4 group A member 1; Nuclear hormone receptor subfamily 4 group A
Gene: Protein-coding gene on chromosome 12 (52,022,832 to 52,059,509, forward strand). Ensembl gene ENSG00000123358.
Subcellular location: Nucleus; Cytoplasm, cytosol; Mitochondrion
Subcellular location (Human Protein Atlas): Nucleoplasm; Cytosol; Nuclear membrane; Nuclear speckles; Nucleoli fibrillar center
Pathways (Reactome):
Disease: Constitutive Signaling by AKT1 E17K in Cancer
Gene expression (Transcription): Nuclear Receptor transcription pathway
Signal Transduction: AKT phosphorylates targets in the nucleus
Gene Ontology:
Molecular function: DNA-binding transcription factor activity, RNA polymerase II-specific; protein binding; sequence-specific double-stranded DNA binding; DNA binding; DNA-binding transcription activator activity, RNA polymerase II-specific; lipopolysaccharide binding; nuclear glucocorticoid receptor binding; nuclear receptor activity; protein heterodimerization activity; RNA polymerase II cis-regulatory region sequence-specific DNA binding; DNA-binding transcription factor activity; double-stranded DNA binding; identical protein binding; sequence-specific DNA binding; zinc ion binding
Biological process: cell migration involved in sprouting angiogenesis; cellular response to fibroblast growth factor stimulus; cellular response to vascular endothelial growth factor stimulus; endothelial cell chemotaxis; positive regulation of endothelial cell proliferation; positive regulation of transcription by RNA polymerase II; cellular response to corticotropin-releasing hormone stimulus; detection of lipopolysaccharide; fat cell differentiation; negative regulation of cell cycle; non-canonical inflammasome complex assembly; regulation of transcription by RNA polymerase II; regulation of type B pancreatic cell proliferation; signal transduction; intracellular receptor signaling pathway; regulation of DNA-templated transcription
Cellular component: cytosol; fibrillar center; mitochondrion; nuclear membrane; nuclear speck; nucleoplasm; nucleus; chromatin; transcription regulator complex
Genetic constraint (gnomAD): Loss-of-function variants: 24 observed, 47.35 expected, observed/expected ratio (o/e) 0.51, 90% interval 0.37 to 0.71. The upper end of that interval is the gene's LOEUF score, 0.71, which puts it in group 2 of 6, group 1 being the genes least tolerant of losing a copy. Missense variants: 669 observed, 814.4 expected, observed/expected ratio (o/e) 0.82, 90% interval 0.77 to 0.88. Synonymous variants: 353 observed, 358.98 expected, observed/expected ratio (o/e) 0.98, 90% interval 0.9 to 1.07.
Homologues: Orthologues: chimpanzee NR4A1 (99% identical), macaque NR4A1 (99% identical), dog NR4A1 (96% identical), pig NR4A1 (95% identical), guinea pig NR4A1 (95% identical), mouse Nr4a1 (92% identical), rat Nr4a1 (91% identical), rabbit NR4A1 (89% identical), tropical clawed frog nr4a1 (64% identical), zebrafish nr4a1 (57% identical), Drosophila melanogaster Hr38 (46% identical), Caenorhabditis elegans nhr-6 (26% identical). Paralogues in human: NR4A2 (55% identical), NR4A3 (49% identical).
Diseases named in the same sentence as NR4A1 in open-access papers:
NR4A1 is named in the same sentence as 451 diseases in open-access papers, as found by Europe PMC text mining. Sharing a sentence is not in itself a finding about the gene and the disease. The quoted sentences say what the papers report.
breast cancer (4,012 papers, 1989 to 2026). A primary or metastatic malignant neoplasm involving the breast. "Overexpression of NR4A1 improved the carcinogenesis of breast cancer cells, whereas its loss had the opposite effect." (PMID 40002690, 2025). "We find two complexes between the up-regulated Bcl2A1 and two down-regulated BH3-only candidates (i.e., Hrk and Nr4a1) as targets associated with reduced apoptosis in breast cancer samples for future experimental validation." (PMID 31825969, 2019). "On the other hand, one study reported that NR4A1 expression was increased in late stage breast cancer and this increase was associated with reduced overall survival." (PMID 28903348, 2017). "Further, we examined whether the elevated NR4A1 expression was associated with an increased survival rate in human breast cancer using NR4A1 gene expression." (PMID 34209871, 2021). "In contrast, NR4A1 is overexpressed in most solid tumor-derived cancers, including breast cancer, and results of knockdown studies demonstrate the role of NR4A1 in regulating pathways and genes associated with cancer cell proliferation, survival, and migration/invasion." (PMID 34072371, 2021). "The long non-coding RNA MALAT1 modulates NR4A1 expression through a downstream regulatory element in breast cancer cells." (PMID 40666103, 2025). "For instance, in certain samples of human breast cancer, NR4A1 gene and protein expressions were decreased to suggest a tumor suppressor role." (PMID 38297314, 2024). "Previous studies in breast cancer cells show that NR4A1 acts as a cofactor of Sp1-mediated expression of PD-L1, and our results confirm a similar pathway in colon cancer cells." (PMID 37847301, 2023). "Similar results were observed in RKO and SW480 cells, indicating that PD-L1 is regulated by NR4A1/Sp1 in colon cancer cells as previously observed in human and mouse breast cancer cells and NR4A1 antagonists decrease expression of this checkpoint gene product." (PMID 37847301, 2023). "NR4A1 plays diverse roles in many tumors, including melanoma, colorectal cancer, breast cancer, and hepatocellular cancer, to regulate cell growth, apoptosis, metastasis." (PMID 36052242, 2022). "Consistent with our analysis, it has been shown that NR4A1 reduced during the development of mouse basal-like mammary tumors and significantly downregulated in human TNBC samples." (PMID 35547878, 2022). "TGF-mediated induction of the EMT is dependent on the nuclear export of NRA41 in breast cancer cells, and NR4A1 antagonists inhibit the nuclear export of NR4A1 and thereby block the TGF-induced EMT." (PMID 35600274, 2022). "In contrast, NR4A1 is overexpressed in many other human malignant tumors, for example, pancreatic cancer, colorectal cancer, and breast cancer." (PMID 36052242, 2022). "Paradoxically, in colorectal, pancreatic, and breast cancer, NR4A1 shows the opposite effect in modulating glycolysis." (PMID 36052242, 2022). "There has a complemental effect between cancer cells and DDA; by binding to the liver X receptor (LXR), DDA can activate NR4A1 expression to exhibit an anti-tumor effect on breast cancer and melanoma." (PMID 36052242, 2022). "In breast cancer, the abnormal expression of NR4A1 imparts suppressive on the proliferative and migrative abilities of cancer cells." (PMID 35311465, 2022). "Loss of NR4A1 inhibits TGF-β-induced epithelial-to-mesenchymal transition (EMT), revealing a novel mechanism by which the microenvironment stimulates breast cancer cell invasion and metastasis." (PMID 33634114, 2021). "To investigate the molecular mechanism by which NR4A1 regulates tamoxifen sensitivity, we performed gene expression profiling using the breast cancer patient dataset retrieved from cBioportal." (PMID 34209871, 2021). "More importantly, high cytoplasmic NR4A1 contributes to apoptosis by inducing the expression of pro-apoptotic factors in breast cancer cells." (PMID 34209871, 2021).
breast cancer (continued). "Other studies on different groups of breast cancer patients gave variable prognostic values for NR4A1." (PMID 34072371, 2021). "In this study a subset of 3,5-disubstituted phenyl CDIM compounds that bound NR4A1 were investigated in a breast cancer model." (PMID 34072371, 2021). "CDIM8 binds NR4A1, and in breast cancer cells CDIM8 inhibits NR4A1-dependent transactivation and mimics the effects of an NR4A1 knockdown." (PMID 34072371, 2021). "Further, the translocation of NR4A1 from the nucleus to the cytoplasm has been found to induce apoptosis in all-trans retinoic acid-induced breast cancer cells." (PMID 34209871, 2021). "A recent study demonstrated that TGF-β-induced nuclear export of NR4A1 is dependent on activation of the p38 MAPK pathway in breast cancer cells." (PMID 33995055, 2021). "To investigate NR4A1 gene expression in tamoxifen-resistant (TamR) breast cancer cells, we examined the mRNA and protein expression levels of NR4A1 in MCF7 and TamR cells using qRT-PCR and western blotting." (PMID 34209871, 2021). "Of note, activation of NR4A1 in breast cancer enhances TGFβ3 signaling, potentiating its oncogenic activities, by inducing SMAD7 degradation." (PMID 33634114, 2021). "NR4A1 protein expression is also decreased in the mouse basal-like mammary tumors during the tumor progression process and in a large proportion of human TN breast cancer (TNBC) tumors." (PMID 33634114, 2021). "Mechanistically, we revealed that NR4A1 restored tamoxifen sensitivity by inhibiting the ERK signaling pathway in tamoxifen-resistant breast cancer cells." (PMID 34209871, 2021). "NR4A1 has been identified as a regulator for fatty acid uptake in breast cancer, leading to restrained fatty acid metabolism and inhibiting breast cancer progression both in vitro and in vivo." (PMID 33634114, 2021). "We also compared the expression of NR4A1 in clinical breast cancer patient samples retrieved from a publicly available dataset (GSE1378, METABRIC)." (PMID 34209871, 2021). "CDIM8 also antagonizes one or more NR4A1-regulated pro-oncogenic pathways or genes in several different breast cancer cell lines including HS578T, SUM159, MDA-MB-231, SKBR3, 4T1 (mouse), and MCF-7 cells." (PMID 34072371, 2021). "A survey of nuclear receptor expression in mammary tumors reported that NR4A1 was overexpressed in both ER-positive and ER-negative tumors but was inversely expressed with a higher histologic grade." (PMID 34072371, 2021). "Specifically, two reports have supported the role of NR4A1 as a tumor suppressor in hematologic and breast cancer, while a third report proposed its role in potentiating TGF-β signaling and promoting metastasis in breast cancer." (PMID 32894083, 2020). "According to Kaplan–Meier plotter, low expression of CD109, ID4, NR4A1, and SYCP3 is associated with poor RFS in breast cancer patients." (PMID 32679794, 2020). "A study showed that in aggressive breast cancer, nuclear orphan receptor NR4A1 expression is strongly induced by the inflammatory cytokines IL-1β and TNF-α." (PMID 30213113, 2018). "A large number of small molecules have been identified, such as C-DIM, which is a NR4A1 antagonist, which induces apoptosis and activates growth inhibitory genes and pathways in breast cancer cells." (PMID 29498706, 2018). "In conclusion, this study demonstrated that inflammation-induced NR4A1 strongly promotes TGF-β-mediated breast cancer cell invasion and metastasis." (PMID 30213113, 2018). "Semi-quantitative analysis of NR4A1 protein expression by immunohistochemistry also identified a progressive NR4A1 reduction during the development of mouse basal-like mammary tumors and a significant NR4A1 downregulation in human TNBC samples." (PMID 28903348, 2017). "Ectopic expression of NR4A1 in ZR-75-1 breast cancer cells with ERα expression and PMC42 breast cancer cells with progenitor characteristics can inhibit cell migration although proliferation and apoptosis of these cells are unaffected." (PMID 28903348, 2017).
breast cancer (continued). "To choose a TNBC cell line for studying the role of NR4A1 expression, we examined NR4A1 protein in several breast cancer cell lines." (PMID 28903348, 2017). "One study reported that about 50% of breast tumors showed NR4A1 overexpression; TNF-α-induced NR4A1 expression in MCF-7 ERα-positive breast cancer cells plays an anti-apoptotic role; and ectopic expression of NR4A1 also promotes MCF-7 cell growth." (PMID 28903348, 2017). "These analyses suggest that the NR4A1 gene transcript is downregulated in human breast cancer including TNBC." (PMID 28903348, 2017). "We report that NR4A1 protein expression is decreased in the mouse basal-like mammary tumors during the tumor progression process and in a large proportion of human TNBC tumors." (PMID 28903348, 2017). "As our first step to explore the role of NR4A1 in cancer, we compared the expression levels of NR4A1 mRNA in human breast cancer and normal breast tissues by analyzing the data sets in the database of Gene Expression Across Normal and Tumor Tissue (GENT)." (PMID 28903348, 2017). "Smaller NR4A1-mRNA amounts are observed in all PAM50 mammary-tumor types relative to the normal gland." (PMID 26894976, 2016). "In breast cancer NR4A1 activity is involved in mediating inflammation-induced epithelial to mesenchymal transition and breast metastasis." (PMID 26131976, 2015). "A previous study identified the transcription factor NR4A1 as a gene upregulated in primary breast cancer compared with normal tissue by microarray analysis and sequencing technologies." (PMID 20642837, 2010). "NR4A1 expression in breast tumours was assessed by semiquantitative and real-time PCR using RNA from normal and tumour samples or breast cancer cell lines." (PMID 20642837, 2010). "NR4A1 acts as an antimigratory factor in two normal mammary epithelial and two breast cancer cell lines tested." (PMID 20642837, 2010). "In the present article we explore the role in mammary cell biology of one transcription factor, namely NR4A1, by its ectopic expression in normal mammary epithelial cells and breast cancer cell lines." (PMID 20642837, 2010). "The purpose of the study was to identify the role of NR4A1 in normal mammary epithelial and breast cancer cell biology." (PMID 20642837, 2010). "The downregulation of NR4A1 in breast cancers of higher grade is therefore possibly due to its adverse effect on the migration of the tumour cells." (PMID 20642837, 2010). "NR4A1 has been shown to mediate apoptosis in several tumour cell lines, including prostate cancer cells, colon cancer cells, breast cancer cells and melanoma cells." (PMID 20642837, 2010). "Both compounds inhibited breast cancer cell growth and induced apoptosis and there was a concordance between the effects of NR4A1 and NR4A2 knockdown and effects of DIM-3,5 analogs in TNBC cells and on several NR4A-regulated genes including EGFR, β1-integrin, bcl-2 and c-Myc." (PMID 41184246, 2025). "These three TFs play important roles in breast cancer development and progression: CUX1 is associated with poor prognosis in ER-positive breast cancer, NR4A1 promotes tumor cell metastasis, and IKZF3 is linked to poor prognosis in HER2+ and regulates cell proliferation." (PMID 40923764, 2025). "In breast cancer, inflammatory factors can induce NR4A1 expression both in vivo and in vitro." (PMID 40666103, 2025). "Alternatively, the presence of NR4A1 in mammary tissues inhibited mammary tumor development." (PMID 40164686, 2025). "Both compounds inhibited breast cancer cell growth and induced apoptosis and there was a concordance between the effects of NR4A1 and NR4A2 knockdown and effects of DIM-3,5 analogs in MDA-MB-231 cells and on several NR4A-regulated genes including EGFR, β1-integrin, bcl-2 and c-Myc." (PMID 40313760, 2025).